EGFR (epidermal growth factor receptor)
Diseases named in the same sentence as EGFR in open-access papers (continued):
Sharing a sentence is not in itself a finding about the gene and the disease.
lung cancer (continued). "One effective approach is using epidermal growth factor receptor tyrosine kinase inhibitors (EGFR-TKIs) that hinder the proliferation of lung cancer cells." (PMID 37242510, 2023). "ROR1 has also been shown to form heterodimers with EGFR, promoting the maintenance of lung cancer cell survival." (PMID 37111634, 2023). "It is well‐known that immunotherapy in EGFR‐mutant lung cancer patients is less efficacious than in patients with EGFR wild‐type lung cancer." (PMID 37699785, 2023). "Osimertinib is an irreversible EGFR‐TKI used to treat T790M‐mediated lung cancer that is resistant to other EGFR inhibitors." (PMID 36650118, 2023). "Several studies have shown promising results in radiomics in detecting EGFR mutations, ALK mutations, and survival prediction in advanced lung cancer patients." (PMID 37697337, 2023). "A radiogenomic model based on 18F-FDG PET/CT radiomics and clinical EGFR has good application value in predicting PFS stratification of lung-cancer patients after SBRT treatment, which can provide a reference to clinical medicine." (PMID 37109413, 2023). "We previously reported that hepatocyte growth factor (HGF), predominantly produced by fibroblasts, plays an important role in lung cancer cell lines that are resistant to EGFR‐TKIs." (PMID 36416133, 2023). "Common targeted therapies for lung cancer include EGFR inhibitors, such as Erlotinib and Afatinib, and ALK inhibitors, such as Crizotinib and Alectinib." (PMID 38026900, 2023). "Opportunistically suppressing AKR1B1 with the selective inhibitor epalrestat (an antidiabetic drug) recovers the sensitivity of resistant cell lines to EGFR TKIs and delays resistance in lung cancer patient-derived xenograft mice." (PMID 37381723, 2023). "EGFR gene mutation subtyping has also been widely adopted in the treatment of lung cancer for selecting targeted drugs against EGFR." (PMID 37575244, 2023). "FGF2-mediated activation of FGFR1 promotes resistance to EGFR inhibitors in lung cancer, FLT3 inhibitors in AML, and KIT inhibitors in gastrointestinal stromal tumors." (PMID 37598282, 2023). "For instance, increased proliferation and increased phosphorylation of ERK occurring in lung cancer cells exposed to growth factor activating EGFR and HER2 were inhibited by DPI incubation." (PMID 37189846, 2023). "The most common mutation seen in non-small cell lung cancer (NSCLC), accounting for approximately 85% of all lung cancer types, is in the tyrosine kinase domain of the epidermal growth factor receptor (EGFR)." (PMID 37927598, 2023). "Osimertinib, a third‐generation EGFR‐TKI, demonstrated superior PFS and OS compared with erlotinib or gefitinib as the initial treatment for patients with EGFR‐mutant lung cancers." (PMID 37016906, 2023). "The proliferation of the PC9 human EGFR-mutant lung cancer cell line completely depends on EGFR signaling, and EGFR tyrosine kinase inhibitors are able to stop it." (PMID 36909198, 2023). "EGFR-TKI monotherapy has been utilized for EGFR mutant lung cancer, and EGF monoclonal antibodies, together with chemotherapy, have been used for breast cancer, gastric cancer, and colon cancer, among others." (PMID 37332342, 2023). "The in vivo study conducted on tumor-bearing mice showed promising results, including anti-proliferative activity and radioactive retention in the tumor, indicating the potential of the system as an effective nano theranostic for EGFR-expressing lung cancer." (PMID 37242668, 2023). "Although primary lung cancers and paired BMs shared pivotal molecular phenotypes, such as the EGFR expression and EML4-ALK fusion status in lung cancer cases." (PMID 37384291, 2023). "Purpose: to develop a radiogenomic model on the basis of 18F-FDG PET/CT radiomics and clinical-parameter EGFR for predicting PFS stratification in lung-cancer patients after SBRT treatment." (PMID 37109413, 2023). "Numerous studies have shown that the stability of the EGFR protein is a key factor in the development of lung cancer." (PMID 37240137, 2023).
lung cancer (continued). "Concurrent with these findings, analysis of public clinical data recorded in the TCGA and GEO databases demonstrated that EGFR-mutant lung-cancer patients whose tumors expressed higher JWA expression were associated with better overall survival." (PMID 37240137, 2023). "Prednisone combined with EGFR inhibition suppressed adaptive resistance also in vivo (e.g., in mouse models of lung cancer), proposing novel treatment concepts for the human disease." (PMID 37686465, 2023). "This potential anoikis-promoting mechanism and metastasis suppressive impact of CTGF with anti-EGFR therapy serve as a therapeutic avenue for lung cancer." (PMID 37091854, 2023). "The strongest associations were observed with Sapitinib, an inhibitor of ErbB1/2/359, Osimertinib, a lung cancer EGFR inhibitor, and Acetalax, a drug used in the treatment of triple-negative breast cancers." (PMID 36774358, 2023). "Targeted therapies that focus on inhibiting the LLPS-mediated activation of the EGFR pathway represent a promising approach for treating lung cancer." (PMID 37580790, 2023). "Some of the current targets for CAR T cells therapy in lung cancer are as follows: EGFR, HER2, mesothelin (MSLN), MUC1, CEA, PD-1, and CD80/CD86." (PMID 36899885, 2023). "We previously demonstrated a positive association of a TKI-induced interferon gamma (IFNγ) transcriptional response with DOT in EGFR-mutant lung cancers." (PMID 36739466, 2023). "JAC4 significantly activated the expression of JWA in lung-cancer cell lines and tumor tissues, thereby inhibiting the growth and metastasis of EGFR-driven lung cancer in vivo and in vitro." (PMID 37240137, 2023). "With regard to lung cancer, the advent of EGFR TKIs has revolutionized the treatment of EGFR-mutant NSCLC and significantly improved the prognosis of these patients." (PMID 36915101, 2023). "In a study of EGFR mutant lung cancer, Nakayama and colleagues (2014) found that ethacrynic acid can reduce lung tumor formation in an in vivo mouse model by inhibiting β-catenin in the Wnt signaling pathway." (PMID 37047688, 2023). "Our results highlight that 8PN has the potential for further development as an adjuvant for improving the efficacy of EGFR TKIs in lung cancer treatment." (PMID 37013960, 2023). "As we previously demonstrated, LAMC2 facilitates EGFR localization at the cell membrane, thereby enhancing EGFR protein stability, which is essential for promoting lung cancer cell growth." (PMID 37542131, 2023). "Among these candidates, curcumin has been shown to reduce EGFR expression in several studies and has been used to treat malignant diseases, including lung cancers." (PMID 37178919, 2023). "In this study, we show that the expression of the lncRNA BC009639 (BC) promotes lung cancer growth and metastasis, and resistance to EGFR‐TKI targeted therapies by regulating EMT." (PMID 36650118, 2023). "To assess the clinical relevance of our observation, we re-visited RNA-seq data of patients with EGFR-mutant lung cancers derived from tumors biopsied prior to and after EGFR-TKI (osimertinib or erlotinib) treatment." (PMID 36817465, 2023). "While the frequency of EGFR-driven lung cancers seems to increase with increasing PM2.5 exposure, there are no changes in the accompanying EGFR mutation pattern, indicating that PM2.5 primarily induces ADC through promotion." (PMID 37696458, 2023). "In conclusion, 8PN enhances the anticancer efficacy of EGFR TKI on lung cancer and triggers neutrophil‐dependent necrosis, highlighting the potential to overcome TKI resistance in lung cancer patients who have EGFR mutation." (PMID 37013960, 2023).
lung cancer (continued). "Among these genes, epidermal growth factor receptor (EGFR) and insulin-like growth factor 1 receptor (IGF1R), which have been shown to be associated with lung cancer metastasis and progression, were selected for further studies." (PMID 37880793, 2023). "In particular, they found that these EGFR-mutant lung cancer cell lines mainly acquired MET amplification as a mechanism of resistance and become sensitive to afatinib plus crizotinib." (PMID 37152062, 2023). "We have also reported that EGFR/KRAS activation drives BH4 production in lung cancer and that blocking EGFR signaling reduces BH4." (PMID 37251335, 2023). "AREG-induced IL-8 production in a human lung cancer cell line (A549) via pathways involving EGFR, PI3K/AKT, and ERK." (PMID 37868614, 2023). "METTL3 promoted lung cancer cell growth, survival, and invasion by increasing the translation process of a set of target oncogenes, including epidermal growth factor receptor (EGFR) and the Hippo pathway effector tafazzin (TAZ)." (PMID 36835633, 2023). "Significant advances in the treatment and outcome of advanced EGFR-mutant lung cancer patients have been achieved with EGFR tyrosine kinase inhibitors (TKIs), especially for those patients with exon 19 deletion or L858R." (PMID 36915101, 2023). "Epidermal growth factor receptor (EGFR) is highly expressed in lung cancer patients and plays a crucial role in various malignancy-related processes." (PMID 37717020, 2023). "GAB1 has been depicted as participating in the mechanism of HGF-induced EGFR-tyrosine kinase inhibitors (TKIs, osimertinib and gefitinib) resistance in lung cancer cell lines." (PMID 37627207, 2023). "A new research front is opening up to explore a potential correlation between variation in methylation levels of specific CpG sites located at promoter and/or gene body regions of EGFR gene and response to EGFR-TKIs in lung cancer patients." (PMID 37152062, 2023). "For lung cancer, most notably EGFR, ALK and PD-L1 expression has had a significant impact on management, however, there is very limited data available of molecular profiles of lung cancer patients in SSA." (PMID 37368872, 2023). "Abnormal YAP activation in the Hippo pathway significantly reduced the efficacy of targeted therapy and enhanced resistance to epidermal growth factor receptor (EGFR) tyrosine kinase inhibitors in lung cancer." (PMID 37151398, 2023). "Western blotting showed a significant reduction in the EGFR and tyrosine phosphorylation bands in breast cancer, prostate cancer, and lung cancer cells treated with FQTT." (PMID 37754201, 2023). "In summary, the current work provides the first proof-of-principle study for the development of an MHC II multi-peptide vaccine against EGFR neoantigens for lung cancer interception." (PMID 36875137, 2023). "Autonomous artificial intelligence (AI) systems combined with CT images can provide noninvasive whole-lung analyses to forecast the projections of lung cancer patients receiving EGFR-TKI therapy." (PMID 37760531, 2023). "Today, EGFR inhibitorsare used in the treatment of cancer typeswith high mortality rates such as lung cancer." (PMID 37663500, 2023). "Non‐small‐cell lung cancer (NSCLC) is the most common type of lung cancer, and many NSCLC patients are diagnosed at advanced stages, two‐thirds of which harbor epidermal growth factor receptor (EGFR) mutations." (PMID 37013960, 2023). "This high dose pulsatile dosing was initiated to deal with brain metastases from EGFR mutant lung cancers and HER2-overexpressing breast cancers." (PMID 37169023, 2023). "Epidermal Growth Factor Receptor (EGFR) mutations, for instance, positively correlate with PD-L1 expression in lung cancer, with EGFR inhibitors acting as repressors of PD-L1 transcription." (PMID 36931099, 2023). "Case reports have detailed the loss of fusion or mutant oncoprotein expression in lineage-transformed TKI-resistant lung cancers, including EGFR-mutant and ROS1-rearranged NSCLC38,39." (PMID 37923925, 2023).
lung cancer (continued). "In this study, among the several mechanisms of adaptive resistance in ALK-rearranged lung cancer cells, we focused on EGFR signaling." (PMID 36702855, 2023). "As we all know, Human Epidermal growth factor Receptor 2 (HER2/ERBB2) and Epidermal Growth Factor Receptor (EGFR) are two crucial biomarkers in the prognosis of lung cancer." (PMID 38137354, 2023). "In lung cancer models, resistance to EGFR targeted therapy was mediated by NF1 expression, and blocking MEK restored the response." (PMID 35702826, 2023). "The effectiveness of EGFR tyrosine kinase inhibitors (TKIs) in prolonging the overall survival and progression-free survival of patients with lung cancer has been thoroughly investigated." (PMID 38022518, 2023). "Lu used a radiomic model to predict EGFR status in lung cancer, and the prediction model using different features achieved AUCs of 0.68, 0.67, and 0.69." (PMID 37644593, 2023). "Decision‐makers in Quebec are increasingly interested in the real‐world effectiveness of breakthrough palliative therapies for advanced lung cancer, like EGFR tyrosine kinase inhibitors (EGFR‐TKI)." (PMID 37017510, 2023). "We previously demonstrated that OBP-301 induces autophagy-related death in human lung cancer cells by suppressing EGFR expression." (PMID 37972012, 2023). "Historically, treatment strategies have focused on expression of key protein targets or targetable mutations, such as HER2 targeted therapy in breast cancer or EGFR targeting in lung cancer." (PMID 37444398, 2023). "Genes related to the β-catenin pathway are found to be abundant in DTP cells from lung cancer patients who have received EGFR TKI treatment." (PMID 36835536, 2023). "The pivotal role of LINC00969 gives it the potential to be a novel biomarker and therapeutic target for overcoming EGFR-TKI resistance in lung cancer." (PMID 37156816, 2023). "The clinical data revealed that the expression of EGFR and IGF1R is associated with poor outcomes in lung cancer patients." (PMID 37880793, 2023). "In clinical trials, the epidermal growth factor receptor (EGFR) inhibitor gefitinib (Iressa) showed anti‐cancer effectiveness against malignancies such as non‐small cell lung cancer and HNSCC." (PMID 37042307, 2023). "MIG6 expression is correlated with EGFR–TKI resistance, and high expression of MIG6 is associated with EMT and poor prognosis in lung cancer." (PMID 37834326, 2023). "20(S)-Ginsenoside Rg3 plays an inhibitory role in lung cancer through regulating EGFR-dependent Ras/Raf/MEK/ERK pathway." (PMID 37305523, 2023). "✓ Promoter hypermethylation inversely correlates with expression levels.✓ High methylation levels at the PD-L1 promoter region are linked to the resistance to anti-PD-1 therapy in both chemotherapy or EGFR-TKI treated lung cancer patients." (PMID 37152062, 2023). "Acquired or secondary resistance to TKIs typically occurs in lung cancer patients after an initial response or stable disease to EGFR-TKIs (≥ 6 months), according to the RECIST criteria." (PMID 37152062, 2023). "Tyrosine kinase inhibitors are currently applied in the treatment of nonsmall cell lung cancer with EGFR." (PMID 37521754, 2023). "The observation is also consistent with a recent report of correlation between high-grade patterns and EGFR TKI resistance in patients with relapsed lung cancer." (PMID 36647832, 2023). "Tyrosine kinase inhibitors (TKIs) have been recognized as the standard treatment for patients with non–small cell lung cancers (NSCLCs) and epidermal growth factor receptor (EGFR) sequence variation." (PMID 37195663, 2023). "Given the dense scientific debate on the role of EGFR and ALK mutations in NSCLC, aimed studies on BMs derived from this specific family of lung cancer should be carried out to explore their impact on diagnosis and treatment prognosis." (PMID 37240478, 2023). "Epidermal growth factor receptor (EGFR)-specific tyrosine kinase inhibitors (TKIs) have changed the landscape of lung cancer therapy." (PMID 37894376, 2023).
lung cancer (continued). "Third, smokers were related to a high incidence of non-EGFR-mutant lung cancers, implying that this factor had a confounding effect." (PMID 36670497, 2023). "For example, EV-associated mutations in oncogenic driver genes, such as EGFR and ALK, have been detected in EV samples from lung cancer patients, and their presence has been correlated with the tumor mutational status and treatment response." (PMID 37240238, 2023). "EGFR inhibition halted ALK-rearranged lung cancer cell proliferation by enhancing ALK inhibition-induced apoptosis via suppression of Bcl-xL." (PMID 36702855, 2023). "Osimertinib (AZD9291), a third‐generation EGFR–TKI, presented a superior clinical response and outcome in EGFR‐mutated non‐small cell lung cancer (NSCLC)." (PMID 37229486, 2023). "In PDPN-positive CAFs from lung tumors, the CAFs promote lung cancer cell resistance to inhibitors of EGFR." (PMID 37894446, 2023). "Epidermal growth factor receptor (EGFR) is a tyrosine kinase receptor and plays a crucial role in the initiation and developemnt of multiple malignancies, such as lung cancer, breast cancer, glioblastoma, and colon cancer." (PMID 37305523, 2023). "Emut Vax was very effective to prevent tumor development, which showed a 75% decrease in tumor volume in a highly aggressive transgenic model that recapitulates salient features of human EGFR lung cancers." (PMID 36875137, 2023). "Epithelial–mesenchymal transition (EMT) and AXL overexpression are often observed in EGFR–TKI–resistant lung cancers." (PMID 37834326, 2023). "Since it is often difficult to obtain adequate tissue samples for EGFR testing in patients with advanced lung cancer, liquid biopsy has been the promising surrogate sample." (PMID 36621813, 2023). "To examine the relationship between air pollutants and EGFR-driven lung cancer incidence, we used several ecological correlation analyses, acknowledging that these analyses only provide estimates of incidence." (PMID 37020004, 2023). "EGFR-directed Tyrosine Kinase Inhibitors (EGFR-TKIs), which have several generations, have been found effective in a type of lung cancer called non-small cell lung cancer (NSCLC) when compared to conventional, platinum-based chemotherapy." (PMID 37190312, 2023). "To further investigate the relationship between LAMC2 and EGFR, we proceeded to examine the location of LAMC2 and EGFR interaction in lung cancer cells." (PMID 37542131, 2023). "First, the study’s sample size was limited, as only 123 lung-cancer patients had undergone 18F-FDG PET/CT within 1 month before SBRT treatment, and only 25 had EGFR mutations." (PMID 37109413, 2023). "The QDs were developed for targeted NIR imaging and treatment of lung cancer via low and high epidermal growth factor receptors (EGFR)." (PMID 37764594, 2023). "The elevation of CD109 promotes metastasis and drug resistance in lung cancer by activating the epidermal growth factor receptor (EGFR)–protein kinase B (AKT)–mammalian target of rapamycin (mTOR) signaling pathway." (PMID 37373457, 2023). "Osimertinib, an oral, third-generation, irreversible EGFR-TKI, was initially approved for the treatment of NSCLC patients carrying EGFR T790M mutations, and has currently become the dominant first-line targeted therapy for most EGFR mutant lung cancer." (PMID 37041601, 2023). "Abnormal epidermal growth factor receptor (EGFR) expression is common in lung cancer; it is involved in cancer initiation, development, metastasis, and treatment resistance." (PMID 36831545, 2023). "For example, chaetoglobosin G hinders cell proliferation and autophagy in lung cancer via EGFR/MEK/ERK network." (PMID 37305523, 2023). "To investigate the cellular response occurring after the acquisition of resistance to EGFR tyrosine kinase inhibitors (TKIs) in lung cancer, we generated a gefitinib‐resistant cell line using EGFR‐mutant HCC827 cells." (PMID 37212485, 2023).